MIR591 (microRNA 591)
Synonyms: hsa-mir-591; MIRN591
Gene: MicroRNA gene on chromosome 7 (96,219,662 to 96,219,756, reverse strand). Ensembl gene ENSG00000208025.
Diseases named in the same sentence as MIR591 in open-access papers:
MIR591 is named in the same sentence as 1 disease in open-access papers, as found by Europe PMC text mining. Sharing a sentence is not in itself a finding about the gene and the disease. The quoted sentences say what the papers report.
breast carcinoma (1 paper, 2025). "Similar effects of tryptase were also seen for a number of other genes implicated in breast cancer, as shown for ARRDC3 and Mir591." (PMID 41145489, 2025).